IL1B (interleukin 1 beta)
Diseases named in the same sentence as IL1B in open-access papers (continued):
Sharing a sentence is not in itself a finding about the gene and the disease.
encephalitis (41 papers, 2012 to 2025). An acute inflammatory process affecting the brain parenchyma. "JEV infection is a common cause of acute and epidemic viral encephalitis, causes the robust microglial activation, and increases the IL-1β production that increases the severity of infection." (PMID 29885667, 2018). "IL-1β has a protective effect against encephalitis caused by HSV-1." (PMID 38590522, 2024). "Using the new animal model, we proposed that patient-derived PBMC might trigger encephalitis pathogenesis by causing Il-1β-dependent BBB dysfunction, and that the IL1 receptor antagonist Anakinra is a potential treatment for anti-NMDAR encephalitis." (PMID 37443034, 2023). "Similarly, IL1β was one of the key cytokines correlating with the severity of HSV1-associated encephalitis and neural invasion in vivo." (PMID 33499363, 2021). "Similarly, IL-1β-/- mice are more susceptible to herpes simplex virus 1 (HSV1)- mediated encephalitis due to an increase in viral load." (PMID 26367131, 2015). "Menopause is a physiological condition that triggers encephalitis, leading to the production of cytokines such as interleukin-1β (IL-1β), IL-1α, and IL-6." (PMID 40292265, 2025). "It is notable that IL-1β was one of the most upregulated genes in mice with anti-NMDAR encephalitis." (PMID 37443034, 2023). "We then examined the therapeutic value of Il-1β blockage in the humanized mouse model of anti-NMDAR encephalitis." (PMID 37443034, 2023). "Proinflammatory factors IL-6, TNF-α, IL-1β were found significantly higher in patients with encephalitis and NPE than those with mild disease." (PMID 36386168, 2022). "Compared to HC, patients with encephalitis or encephalopathy presented elevated IL-6 and IL-8 in both serum and CSF, whereas IL-10, IL-1RA, IL-1b and MIG were elevated only in serum, and MCP1 only in CSF (data not shown)." (PMID 35479062, 2022). "In contrast, compared to HC, patients with encephalitis had elevated serum levels of IL-1b and CSF levels of G-CSF, IL-18 and MIG." (PMID 35479062, 2022). "We chose markers that have already been associated with viral encephalitis and neurodegenerative diseases, including tumor necrosis factor alpha (TNFα), interleukin 6 (IL6), and interleukin 1 β (IL1β)." (PMID 33407600, 2021). "The present study revealed an independent protective association between decreased frequency of G allele in IL-1β rs16944 and Anti-NMDAR encephalitis." (PMID 33362683, 2020). "Genotype and allele frequencies of IL-1β, IL-4, IL-6, IL-10, and IL-17 in anti-NMDAR encephalitis and control groups." (PMID 33362683, 2020). "Elevated level of IL-1β have been demonstrated in the serum of both EV71-infected patient with encephalitis and mouse models." (PMID 29440739, 2018). "All 12 cytokines/chemokines investigated were increased significantly in the IAV pneumonia model compared with the control, whereas all factors other than IL-1β increased significantly in the IAV encephalitis model compared with the control." (PMID 28912622, 2017). "Further research is clearly needed to evaluate the key factors involved in the facilitation of epileptogenesis by viral encephalitis, and more specifically to establish the role of IL-1β." (PMID 27955671, 2016). "The synergistic effects of IL-1β and TNF-α were associated with protection against encephalitis by the neurotropic virus HSV-1 while IL-1β−/− animals showed increased pathogenesis and lethality to Sindbis virus." (PMID 23209411, 2012). "Consistent with clinical features of EV71 patients with encephalitis and PE, who are presented with higher levels of the proinflammatory cytokines in blood, IL-6, IL-1β and TNF-α were induced in EV71-infected MDMs." (PMID 22994237, 2012). "The release of IL-18 and IL-1β from monocytes/macrophages is critical for protection from HSV-1 based on animal models of encephalitis and genital infection, yet if and how HSV-1 activates inflammasomes in human macrophages is unknown." (PMID 32101570, 2020).
encephalitis (continued). "In encephalitis, parenchymal brain inflammation, the ratio of IL-1Ra to IL-1β in the cerebrospinal fluid can be indicative of patient outcomes, with a higher ratio of IL-1β to IL-1Ra indicative of poor patient outcome, and associated with reduced integrity of the BBB." (PMID 31293586, 2019). "Thus, we investigated the role of Il-1β in the pathogenesis of encephalitis in humanized PBMC mice." (PMID 37443034, 2023). "CASP-1, IL-1β, and IL-18 were also expressed in the brain of mice with advanced rabies encephalitis (infected intramuscularly), at higher levels compared to the values that we obtained from the mice that had been infected intracranially and euthanized before advanced signs of encephalitis appeared." (PMID 29615985, 2018). "Animals lacking IL-1β, IL-6, or IL-12 may be resistant to fatal encephalitis or seizures caused by encephalitis, or have reduced neurological severity scores." (PMID 29670611, 2018). "Briefly, the encephalitis groups exhibited increased GFAP, sTREM2, YKL-40, and IL-1β compared to controls, with similar findings in the Cov-Enceph and Enceph groups." (PMID 40036349, 2025). "Meanwhile, key inflammatory mediators (MCP1, IL1β, IL6, TNFα) were significantly elevated in NCG-hSTAT2+/+ mice during viral neuroinvasion, likely driving encephalitis pathogenesis." (PMID 40855992, 2025). "Nevertheless at 14 dpi, BeAn-infected IFN-β-/- mice showed a stronger encephalitis and astrogliosis, higher viral load as well as higher mRNA levels of Isg15, Eif2ak2 (PKR), Tnfa, Il1b, Il10, Il12 and Ifng in the cerebrum than BeAn-infected WT mice." (PMID 35222374, 2022). "We did not identify any significant differences in SNP genotypes of IL-1β, IL-4, IL-6, IL-10, and IL-17 between anti-NMDAR encephalitis and control groups." (PMID 33362683, 2020). "Concentrations of IL‐1β, IL‐6, and IL‐17A dramatically increased in anti‐NMDAR encephalitis group compared with controls (p < 0.0001)." (PMID 31313506, 2019). "IL-4 CCL11, CCL17, CCL21), Th17 (IL-17A, GM-CSF), B cell molecules (BAFF, APRIL) and other cytokine/chemokines including IL-21, IL-1b, IL-12p40, CCL2 and IL-12p70 were detected in less than 50% of patients with encephalitis." (PMID 27575749, 2016). "Some studies have reported that influenza viruses result in encephalitis and encephalopathies, as the related neuronal cells release potentially cytotoxic substances such as TNF‐α, IL‐1β, oxygen radicals and nitric oxide, which also trigger apoptosis and autophagy in the infected cells." (PMID 38683122, 2024). "It has been reported that high levels of cytokines such as IL-1β, IL-6, IL-10, and IFN-γ are correlated with clinical severity in patients with pulmonary oedema and encephalitis, indicating that the immune response of the hSCARB2 mouse model was similar to that of humans." (PMID 34044752, 2021). "Influenza virus may lead to encephalitis and encephalopathy by activating glial cells to release potential cytotoxic substances, such as TNF-α, IL-1β, NO, and oxygen-free radicals." (PMID 33953861, 2021). "In earlier reports, levels of IL-1β, IL-6 and TNFα were found to be significantly elevated in fatal EV-A71 patients with encephalitis and pulmonary oedema, when compared to patients with no complications." (PMID 32123257, 2020). "Furthermore, monocyte/macrophage production of IL-1β and IL-18 is critical to prevent severe HSV disease in encephalitis, keratitis, and vaginal infection in mouse models." (PMID 32101570, 2020). "Thus, IL-1β production by monocyte-derived macrophages and neutrophils is crucial for development of anti-NMDAR encephalitis." (PMID 33362683, 2020). "Previous studies have found that IL-6, IL-1β, IL-8, tumor necrosis factor-alpha (TNF-α), monocyte chemotactic protein-1 (MCP-1), and granulocyte-macrophage colony-stimulating factor (GM-CSF) was highly elevated either in serum or CSF of patients with COVID-19 related encephalitis." (PMID 37384050, 2023).
allergic asthma (40 papers, 2012 to 2026). A asthma with a basis in a pathological type I hypersensitivity reaction. "Supporting this, Th2 response and eosinophilic lung inflammation are significantly reduced in IL‐1β‐ and IL‐1R1‐deficient mice in a murine model of allergic asthma." (PMID 35988262, 2022). "OVA-induced allergic asthma and associated IL-1β production were alleviated in mice with small GTPase Arf6-deficient macrophages." (PMID 34423792, 2021). "IL1B, essential for mediating inflammatory responses, promotes neutrophil recruitment to epithelial cells and is linked to allergen sensitization and the development of allergic asthma." (PMID 40420184, 2025). "Additionally, IL-10 and IL-1β gene polymorphisms are associated with allergic asthma in children and the association between IL-13 polymorphisms and susceptibility to childhood asthma has been extensively studied." (PMID 36313877, 2022). "The findings of various studies indicate that NLRP3 inhibitors, such as OLT1177® can decrease NLRP3 activity, reduce the release of proinflammatory IL-1β, and alleviate pathophysiological features in mouse models of allergic asthma." (PMID 39364406, 2024). "Here, we found that VISTA deletion promotes the M1 polarization and inhibits the M2 polarization both in BMDMs and in OVA-induced allergic asthma, with reduced expression of inflammatory-related genes, such as Il1b and Tnf-a." (PMID 38340268, 2024). "Again, the exacerbation of these allergic asthma phenotypes by IL-1β was observed not only in WT mice but also in Tslp−/− mice." (PMID 36050303, 2022). "IL-1β can stimulate Th2 cells and increase the eosinophils in the lung inflammation site, thus mediating the development process of allergic asthma." (PMID 35431951, 2022). "For the sake of exploring the regulation of inflammatory factors of FDCM in OVA-sensitized allergic asthma, the expression of IL-1β and IL-6 was detected by Western blotting." (PMID 35431951, 2022). "In allergic asthma, pentraxin-3 is produced by immune and structural cells and is up-regulated by pro-asthmatic cytokines such as TNFα and IL-1β." (PMID 35387000, 2021). "Excessive nucleotide-binding oligomerization domain-like receptor family, pyrin domain-containing 3 (NLRP3) inflammasome and concomitant IL-1β responses play a critical role in steroid-resistant SA and promote Th17 allergic asthma in mice." (PMID 34777398, 2021). "We found that the nasal administration of SecinH3 reduced IL-1β production and ameliorated the exacerbation of allergic asthma." (PMID 34423792, 2021). "IL-1α, IL-1β, and IL-1R1 are involved in several models of lung inflammation such as in allergic asthma induced by ovalbumin or cigarette smoke/viral exacerbation models." (PMID 29867931, 2018). "AHR considered as a hallmark of allergic asthma, may also be evoked by neutrophilia and increases in pro-inflammatory cytokines such as TNF-α and IL-1β." (PMID 37464447, 2023). "IL-1β and IL-6 were two inflammatory factors related to allergic asthma." (PMID 35431951, 2022). "The present data do not support a role of IL-1β in allergic asthma since inflammatory effects of HDM alone were not reduced in IL-1β-deficient mice." (PMID 29361942, 2018). "Our previous study found that TLRs on peritoneal macrophage promotes the allergic asthma by maintaining the NLRP3/IL-1β signaling, but in this study, activation of TLRs signaling in sensitization-recruited monocytes could attenuate allergic asthma by producing Th1-associated cytokines." (PMID 30510553, 2018). "Especially in neuroinflammation, studies have reported a reduction in the production of cytokines, such as IL-1β, IL-6, TNF-α, IL-12, and IL-17, and chemokines, such as IFN-Ɣ, MCP-1, MIP-1a, and MIP-1b in allergic asthma." (PMID 40243683, 2025).
allergic asthma (continued). "HDM activates airway epithelial cells via Toll-like receptor (TLR), leading to NF-κB activation and secretion of pro-inflammatory cytokines, such as IL-6 and IL-1β, and also activates NLRP3 to promote HDM-induced inflammatory response in allergic asthma." (PMID 39364406, 2024). "With the additional control of lung IL-1β, IL-6, and TNF-α levels after OVA inhalation exposure, trifuhalol A has strong potential to be further evaluated as a therapeutic candidate for allergic asthma." (PMID 37998734, 2023). "In allergic asthma, it is produced by both immune and structural cells, and its upregulation is induced by pro-asthmatic cytokines such as TNF and IL-1β." (PMID 35387000, 2021). "Morin treatment downregulated the expression of BLT2, NF-κB, and Th2-cytokine (IL-1β, IL-4, IL-6, IL-13, and TNF-α) in the lungs of an allergic asthma rat model." (PMID 33917985, 2021). "Further, BHT down-regulated expression levels of pro-inflammatory cytokines, such as TNF-α, IL-1β, IL-6, IL-8 and IL-17A indicating that BHT has an effect on declining pro-inflammatory response for allergic asthma." (PMID 32397290, 2020). "It reduced the IL-1β, IL-6, TNF-α, and TGF-β level in OVA-induced allergic asthma both in antibiotic-free and antibiotic-treated mice notably, indicating an anti-inflammatory effect in the OVA-induced allergic asthma model." (PMID 33456673, 2020). "It shows ability to inhibit the production of inflammatory mediators, such as IL-1β, IL-6, and TNF-α in macrophages and in mice with allergic asthma." (PMID 30809149, 2019). "Pro-inflammatory cytokine IL-1β is considered to be the gatekeeper of inflammation based on its ability to control multiple immune responses, including OVA-induced allergic asthma, which proved its necessity in producing another pro-inflammatory cytokine release." (PMID 37998734, 2023). "Without being involved in the baseline HDM-induced allergic asthma, IL-1β signalling was required to induce neutrophil chemotactic factors, IL-33, and Muc5ac expression at viral stimulus-induced exacerbation." (PMID 29361942, 2018). "Our work shows a differential requirement for TSLP in these two contexts, and identifies an important function for IL-1β, which is independent of TSLP, in promoting allergen sensitization and subsequent allergic asthma." (PMID 36050303, 2022). "Our study implicates a differential requirement for TSLP in these two contexts, and identifies an important function for IL-1β, which is independent of TSLP, in promoting allergen sensitization and subsequent allergic asthma." (PMID 36050303, 2022).
autism (40 papers, 2011 to 2025). Persistent deficits in social interaction and communication and interaction as well as a markedly restricted repertoire of activity and interest as well as repetitive patterns of behavior. "In children with autism, elevated levels of IL-1β are associated with cognitive dysfunction and deficits in social behaviour." (PMID 40002751, 2025). "This study aimed to evaluate the association between CMV IgG levels and IL-6 and IL-1β cytokine profiles in children with autism aged 2–5 years to assess their correlation with autistic behaviours in the high-burden CMV region." (PMID 40002751, 2025). "Interventions aimed at reducing IL-1β activity have demonstrated the potential to alleviate specific symptoms associated with autism." (PMID 40002751, 2025). "A correlation with the severity of ASD was also observed, with IL-4 being associated with severe forms of ASD (according to the Autism Diagnostic Surveillance Scheme score) and IL-1β with mild ASD forms." (PMID 39125780, 2024). "The main mechanisms underlying the role of these cytokines in autism pathology include IL-1β stimulation of IL-6 production as the main effector of microglial activation after an infection or injury." (PMID 35328471, 2022). "IL-6 and IL-1β are proinflammatory cytokines commonly linked to the pathophysiology of autism and may affect autistic behaviour." (PMID 40002751, 2025). "High levels of IL-6 and IL-1β have been also associated with more severe behavioural deficits in children with autism, while high levels of the anti-inflammatory marker IL-10 have been found in individuals with mild autism-related behavioural impairments." (PMID 36451209, 2022). "This was contrary to expectation given studies such as one examining children with 22q11 deletion syndrome (at high risk of autism) that found that level of IL-1β in the blood, and the ratio of IL-6:IL10 in serum was significantly associated with social scores on the ADI-R." (PMID 30498564, 2018). "Elevated levels of IL-6 and IL-1β play a crucial role in regulating immune responses and are frequently linked to chronic inflammation, which may affect brain development and behaviour in children with autism." (PMID 40002751, 2025). "In various studies, TNF‐α, IL‐1β, and IL‐6 levels were found to be higher in autism groups compared to controls." (PMID 39401991, 2025). "The inflammatory profile in autism is marked by an abundance of pro-inflammatory mediators, such as increased levels of IL-1β, IL-6, IL-8, TNF-α, and interferon-γ." (PMID 41425587, 2025). "Research indicates that children with autism exhibit elevated levels of pro-inflammatory cytokines, including interleukin-6 (IL-6) and interleukin-1 beta (IL-1β), alongside reduced levels of anti-inflammatory cytokines, such as interleukin-10 (IL-10)." (PMID 40002751, 2025). "Multiple meta-analyses have investigated the involvement of IL-6 and IL-1β in autism, revealing that increased levels of these cytokines correlate with heightened autism symptom severity, especially in social communication and repetitive behaviours." (PMID 40002751, 2025). "tVNS application increased brain NLRP3 levels and reduced serum IL‐1β and IL‐22 levels in the autism model." (PMID 39401991, 2025). "The results show that, within the ASD group, the subscales of food refusal, autism characteristics, and limited variety display a correlation with IL-6 and IL-1β." (PMID 40002751, 2025). "Increased levels of pro-inflammatory cytokines, such as interleukin-17 A (IL-17 A), tumor necrosis factor-alpha (TNF-alpha), and interleukin-1 beta (IL-1β), have been observed in the blood and cerebrospinal fluid of individuals with autism." (PMID 38475688, 2024). "Key cytokines and their receptors investigated in relation to childhood autism include IL-17 A, IL-1β, IL-2R, IL-4, IL-6, and various interleukins, each with diverse cellular origins and target cell types." (PMID 38475688, 2024).